ULK4P3 (ULK4 pseudogene 3)
Synonyms: D-X; formerly FAM7A3
Gene: Transcribed unprocessed pseudogene on chromosome 15 (30,110,302 to 30,127,785, forward strand). Ensembl gene ENSG00000178081.
Diseases named in the same sentence as ULK4P3 in open-access papers:
ULK4P3 is named in the same sentence as 1 disease in open-access papers, as found by Europe PMC text mining. Sharing a sentence is not in itself a finding about the gene and the disease.
ULK4P3 shares sentences with these, for which no sentence is quoted: bladder cancer (1 paper).